VDR (vitamin D receptor)
Diseases named in the same sentence as VDR in open-access papers (continued):
Sharing a sentence is not in itself a finding about the gene and the disease.
breast cancer (continued). "In analyses where all women were included, a negative VDR expression was associated with a relatively higher breast cancer mortality in the crude (HR: 2.08, 95% CI: 1.30–3.32) and the adjusted (HR: 1.62, 95% CI: 0.99–2.65) analyses, although adjustments attenuated the results." (PMID 36014861, 2022). "Therefore, lncRNAs can be involved in vitamin D3/VDR signaling, and the vitamin may regulate the expression of lncRNAs that may be important in breast cancer." (PMID 35328609, 2022). "Since transcriptomic data of lncRNAs in neuropsychiatric disorders were not sufficient to perform similar approach to find VDR-associated lncRNAs in these disorders, we suppose that the observed associations between lncRNAs and VDR in breast cancer can also been detected in these disorders." (PMID 35279108, 2022). "Although the responsiveness to calcitriol treatment could be associated with not only the molecular subtype but also the vitamin D receptor (VDR) expression in breast cancer cells, considering that the VDR expression of breast cancer cell lines in our study was verified in previous studies." (PMID 35269680, 2022). "Other pathways and mechanisms may contribute to vitamin D3/VDR signaling in breast cancer." (PMID 35328609, 2022). "The hypothesis that pre-diagnostic vitamin D levels would associate with VDR expression in subsequent breast cancer could not be confirmed with statistical evidence in this study." (PMID 36014861, 2022). "Since VitD upregulates VDR expression, and VDR is known to repress autophagy in human breast cancer cells and in mice, we hypothesized that VitD can inhibit the pro-survival autophagy that is initiated by treating antiestrogen-resistant breast cancer cells with tamoxifen (TAM)." (PMID 34069442, 2021). "Therefore, even though PTPH1 exerts oncogenic activity via modulation of VDR dynamics, the phosphatase may be useful as a marker for heightened breast cancer sensitivity to antihormone therapies." (PMID 34884670, 2021). "Vitamin D receptor is expressed by normal lobule, ductal epithelial cells, stromal and immune cells, adipose cells of human breast and in a higher rate in breast cancer lesions (though there exists some data on the contrary) and in invasive cancers, as compared to in situ cancers or normal tissue." (PMID 34638264, 2021). "Furthermore, miR-125b mimics degrade the endogenous VDR protein level in breast cancer 3,18." (PMID 33390783, 2021). "Therefore, here we attempt to present the complex aspects of SR molecular function in breast cells, including an in-depth description of PR, AR, GR, MR and VDR and their vast interactomes, understanding of which is crucial for developing new approaches in breast cancer endocrine therapy." (PMID 34638264, 2021). "Since VitD upregulates VDR, also in our study, our findings and findings by others provide convincing evidence that VitD supplementation of deficient patients may improve prognosis among TAM-treated breast cancer patients." (PMID 34069442, 2021). "However, VDR mRNAs in breast cancers were 5′-trunctated in most cases." (PMID 32456160, 2020). "Therefore, some breast cancer cases carry a triple biomarker signature—the levels of nuclear VDR, CTSL and TP53BP1 that may be exploited in projecting a treatment strategy in TNBC cases." (PMID 32456160, 2020). "Therefore, chemical demethylation of the VDR gene may reverse 1,25(OH)2D insensitivity in breast cancer cells and make them prone to various 1,25(OH)2D-based therapies." (PMID 32456160, 2020). "Therefore, VDR may induce factors that transactivate the BRCA1 gene and its expression mediates the antiproliferative effect of 1,25(OH)2D, but this pathway may be disrupted in breast cancer by pathogenically mutated BRCA1 or/and aberrant VDR signaling." (PMID 32456160, 2020).
breast cancer (continued). "As regards to HRs calculated for different cytoplasmic VDR scores, they showed similar results as for nuclear VDR expression, i.e., more VDR expression was associated with decreased risk of breast cancer death, but not statistically significant when adjusted (0.59, 0.30–1.16)." (PMID 31358030, 2019). "Furthermore, VDR expression was associated with clinical prognostic factors such as tumour size and lymph node involvement in breast cancer, suggesting that VDR expression may be clinically significant and VDR may be a factor with prognostic relevance." (PMID 29659618, 2018). "Studies in melanoma skin cancer, breast cancer, oesophageal squamous cell carcinoma and urothelial bladder cancer have also found similar findings with improved overall survival and progression free survival in patients with higher VDR expression within the tumour tissue." (PMID 30344947, 2018). "As VDR, RXR and PPARγ can be quantified in cancer tissue easily, they - given them being present in BRCA1 mutated breast cancer cases at all - may evolve as novel alternative biomarkers, especially for hormone receptor negative or even triple negative breast cancer patients." (PMID 28427429, 2017). "The Vitamin D receptor (VDR) expressed in normal breast tissue and breast tumors has been suggested as a new prognostic biomarker in breast cancer (BC)." (PMID 28632174, 2017). "Patients carrying a BRCA1 germline mutation overexpressed VDR (BRCA1mut vs. sporadic: IRS 6.00 vs. IRS 3.00%, p < 0.001), RXR (BRCA1mut vs. sporadic: IRS 6.00 vs. IRS 3.00, p = 0.010) and PPARγ (BRCA1mut vs. sporadic: IRS 2.00 vs. IRS 0.00, p < 0.001) when compared to sporadic breast cancer." (PMID 28427429, 2017). "Therefore, we next tested the hypothesis that the cytoplasmic VDR controls breast cancer cell growth." (PMID 28460457, 2017). "Hence the current study aimed to investigate VDR, RXR and PPARγ in BRCA1mut breast cancer and to test whether any of the three may be associated with clinico-pathological criteria including overall survival." (PMID 28427429, 2017). "Our VDR knockdown results suggest a different role than expected and have led us to propose that the cytoplasmic VDR could be a factor contributing to the regulation of breast cancer cell proliferation." (PMID 28460457, 2017). "Similarly, VDR repression by TNF-α sensitizes breast cancer cells to TGF-β1-induced EMT." (PMID 26880977, 2016). "Cdx2 VDR polymorphism and antiproliferative effects of vitamin D treatment were investigated in a panel of estrogen receptor-positive (MCF7 and T-47D) and estrogen receptor-negative (MDA-MB-231, SUM 159PT, SK-BR-3, BT549, MDA-MB-468, HCC1143, BT20 and HCC1954) human breast cancer cell lines." (PMID 25849303, 2015). "In conclusion, our study provides evidence that the b allele of the BsmI in the VDR gene may be associated with an increased breast cancer risk in Pakistani women who are negative for BRCA1/2 germline mutations." (PMID 26517870, 2015). "Moreover, VDR expression negatively correlates with human breast cancer metastasis." (PMID 26008979, 2015). "Our results may suggest a potential effect of Cdx2 VDR polymorphism on the efficacy of vitamin D treatment in aggressive breast cancer cells (estrogen receptor negative)." (PMID 25849303, 2015). "The BsmI polymorphism in the VDR gene may be associated with an increased breast cancer risk in Pakistani women negative for BRCA1/2 germline mutations." (PMID 26517870, 2015). "Besides its physiological role, 1,25(OH)2D3 is a potent inhibitor of breast cancer (BC) cell growth, exerting its anticancer effect through the binding of VDR, which induces the activation of a series of genes involved in cell growth, differentiation and apoptosis." (PMID 25849303, 2015).
breast cancer (continued). "Moreover, low levels of calcitriol are associated with disease progression and high incidence of ER-negative and triple-negative breast tumors, while VDR-positive breast cancer patients had significantly longer disease-free survival than those with VDR-negative tumors." (PMID 24678876, 2014). "Since the VDR-ApaI a allele is most common in Hispanic/Latinas, and the Latinas in the present study were slightly younger than the African-American subjects, these findings may potentially implicate VDR-ApaI in the progression of cancer among younger breast cancer patients." (PMID 23554871, 2013). "VDR haplotypes are associated with breast cancer in African-Americans, but not in Hispanic/Latinas." (PMID 23554871, 2013). "These include EMT (TWIST1, SNAIL1, RUNX1, RUNX2, HIF1, and NOTCH1), breast cancer maintenance (OCT4, SP1, GATA1, ATF1, FOXO3a, ELK1, VDR, and NRF1), pro-metastatic responses (SMAD2/3, HNF1a, GLI1, NANOG, YY1, MYB1, and AP1), and immune modulation (STAT1/3)." (PMID 38398186, 2024). "Estradiol upregulated the expression of the VDR in MCF-7 cells, and 1,25D3 induced expression of ERα in patients’ breast cancer cells to restore antiestrogen responsiveness." (PMID 39273194, 2024). "Another study reported that vitamin D inhibits the proliferation of breast cancer cells via activating IGFBP3, a target of the VDR and a functional activator of VDRE." (PMID 39335182, 2024). "This approach has been first used in the context of breast cancer and led to identification of MALAT1, SNHG6, LINC00511 and LINC00346 as VDR-related lncRNAs." (PMID 35279108, 2022). "Overall, calcitriol is a natural vitamin D receptor (VDR) agonist; hence, it can reduce cell viability in breast cancer cell lines that are VDR−positive." (PMID 36145297, 2022). "Activation of VDR with vitamin D (VitD), either calcitriol or its synthetic analog EB1089, sensitized MCF-7-derived, antiestrogen-resistant LCC9 human breast cancer cells to TAM, and attenuated increased UPR and pro-survival autophagy." (PMID 34069442, 2021). "In this study we tried to evaluate the Immunohistochemical expression of VDR and CTLA4 antidodies and their role in breast cancer of Egyptian patients as there is a great controversy about their role in suppression or promotion of breast cancer." (PMID 33906311, 2021). "The essential role of VDR in mediating vitamin D anticancer effects in TNBC was shown by LaPorta and Welsh, who demonstrated that 1,25(OH)2D downregulated genes related to breast cancer invasion and metastasis in cells from a mouse model of TNBC." (PMID 32456160, 2020). "(2016) showed that calcitriol (1 uM, 72 h) and calcipotriol (1 uM, 72 h), a VDR agonist, inhibited the expression of KCa1.1 channels in MDA-MB-453 breast cancer cells." (PMID 32210800, 2020). "We found weak evidence for the association of risk variants rs294174 (ESR1), rs16886165 (MAP3K1), rs2214681 (CNTNAP2), rs4237855 (VDR), rs9594579 (RANKL), rs8183919 (PTGIS), rs2981582 (FGFR2), and rs1799950 (BRCA1) with sporadic breast cancer." (PMID 33126731, 2020). "We first examined the expression of Ki67, ER, progesterone receptor (PgR), AR, and VDR and the phosphorylation of AKT Ser473 and ERα Ser167 by immunohistochemistry (IHC) in breast cancer tissues in pre- (n = 62) and postmenopausal (n = 152) women." (PMID 29707142, 2018). "The previously reported inhibition of CD44 expression in breast cancer cells by calcitriol analogue BXL0124 can be blocked by downregulation of VDR, suggesting that the VDR plays a critical role in the regulation of CSC population by calcitriol." (PMID 29581858, 2018). "In human breast cancer cells, PTPH1 regulates cancer cell growth by its stimulatory effect on VDR via its binding to VDR in the cytoplasm." (PMID 28460457, 2017). "However, neither VDR nor RXR nor PPARγ have been studied in BRCA1 associated breast cancer so far." (PMID 28427429, 2017).
breast cancer (continued). "VDR, RXR and PPARγ were even detected in those cancers characterized as both triple negative and highly proliferative - two basic features of basal like breast cancer." (PMID 28427429, 2017). "VDR, RXR and PPARγ were detected in over 90% of triple negative BRCA1mut breast cancer and were significantly (VDR: p < 0.001, RXR: p = 0.010, PPARγ: p < 0.001) overexpressed in BRCA1 mutated as compared to sporadic cancer cases." (PMID 28427429, 2017). "In breast cancer, a single in vitro study has identified that PTPH1 positively regulates breast cancer growth by its stimulatory effect on VDR protein expression." (PMID 28460457, 2017). "Notch signaling was also among the five top pathways altered in the offspring of HF diet-fed dams, in addition to VDR/RXR and FXR/RXR activation, hereditary breast cancer signaling, and PTEN signaling." (PMID 28673325, 2017). "In vitro, in breast cancer cell lines, three hypermethylated regions in exon 1a became demethylated after treatment with the DNMT1 inhibitor 5-aza-2′-deoxycytidine (DAC) and VDR mRNA expression increased." (PMID 24808866, 2014). "The design of the study was conceived to be tested in a murine model xenografted with two human breast cancer cell lines expressing both EAG1 and the VDR." (PMID 25280486, 2014). "However, it is also possible that light skin pigmentation combined with high sun exposure, rather than differences in vitamin D receptor polymorphisms among whites compared to other women, account for the reduction in breast cancer risk limited to this race/ethnic group." (PMID 24438060, 2014). "In this study the role of IGF binding protein-3 (IGFBP-3) in 1, 25-D3-induced apoptosis was investigated using parental MCF-7 breast cancer cells and MCF-7/VDR cells, which are resistant to the growth inhibitory effects of 1, 25-D3." (PMID 23690781, 2013). "Vitamin D receptor (VDR) was significantly down-regulated in mammospheres, as well as in ALDH+ breast cancer cells." (PMID 23341935, 2013). "Overall, our results on the expression of the VDR, CYP27B1 and CYP24A1 suggest that there is a deregulation of the Vitamin D metabolic and signalling pathways in breast cancer, in order to favour tumour progression." (PMID 20831823, 2010). "In summary, this is the first study to report the expression of the VDR, CYP27B1 and CYP24A1 in a series of normal breast, preneoplastic mammary lesions, breast carcinomas in situ and invasive tumours." (PMID 20831823, 2010). "1α,25-Dihydroxyvitamin D3, the biologically active form of vitamin D that interacts with the vitamin D receptor (VDR), is a coordinate regulator of proliferation, differentiation, and survival of breast cancer cells." (PMID 19442290, 2009). "The involvement of vitamin D receptor (VDR), which is a key mediator in the vitamin D pathway, in breast cancer etiology has long been of interest." (PMID 18067661, 2007). "In this study, we demonstrate that calcitriol upregulates VDR expression in HER2-positive breast cancer cells, regardless of their ER status." (PMID 40943316, 2025). "VDR expression and HR, HER2, and molecular subtype in patients with breast carcinoma." (PMID 40898467, 2025). "In breast cancer cells, macrophage-secreted TNF-α inhibits VDR expression." (PMID 39430253, 2024). "Contrasting the differences in VDR expression levels in invasive breast cancer tissues, a cohort study has revealed a negative correlation between VDR expression levels and the degree of tumor malignancy." (PMID 38230221, 2024). "Here we will discuss the known mechanisms of non-steroid hormone receptors RAR, RXR and VDR in breast cancer carcinogenesis as well as recent efforts to target these nuclear receptors for breast cancer prevention." (PMID 37583424, 2023).
breast cancer (continued). "In breast cancers, the VDR promoter was significantly hypermethylated (65%) than in normal breast tissue (15%), supporting the proposed mechanism of silencing VDR expression through promoter hypermethylation, which appears linked to 1,25(OH)2D3 sensitivity." (PMID 38203278, 2023). "The association between VDR expression and breast cancer prognosis was not modified by pre-diagnostic levels of vitamin D. It would be preferable to investigate whether vitamin D levels at diagnosis and VDR expression in a tumor coincide to influence breast cancer prognosis." (PMID 36014861, 2022). "Non-steroidal NRs, such as vitamin D Receptor (VDR) and nuclear receptors for thyroid hormone (TRs), are also expressed in breast cancer and play functional roles in breast cancer cells, although these roles are less critical than that of ER." (PMID 35160139, 2022). "Treatment with the vitamin D analog EB1089 effectively inhibits aromatase-dependent growth of breast cancer cells by dissociating BAZ1B from the CYP19A1 promoter in a vitamin D receptor (VDR)-dependent manner, suggesting that BAZ1B is a potential drug target in breast cancer." (PMID 34736517, 2021). "Furthermore, recent studies have demonstrated that demethylating agents induce VDR expression in AML and in high CEBPα breast cancer cells." (PMID 34680392, 2021). "VDR influences the expression of ITGβ3, SLC1A1, KDR, BIRC3 and GLUL, exerting an antiproliferative phenotype, promotes CYP24A1, SERPINB1, EFTUD1, CLMN, KLK6—The three latter are related to better survival in breast cancer." (PMID 34638264, 2021). "In addition, one and two reports studied vitamin D receptor (VDR)-regulated lncRNAs profiling in skin cancer and breast cancer, respectively." (PMID 34422647, 2021). "Assessment of expression of VDR and these lncRNAs in breast cancer tissues and adjacent non-cancerous tissues (ANCTs) has led to identification of aberrant expression of MALAT1 and LINC00511 in tumoral specimens." (PMID 32514489, 2020). "Accordingly, VDR is expressed in normal breast tissue and in many, but not all, breast carcinoma cell lines and tumors." (PMID 32854355, 2020). "The prognosis of patients with multifocal breast cancer was either not affected by estrogen and/or progesterone receptor expression or even involved a worse etiopathology for the vitamin D receptor-positive patients." (PMID 31731733, 2019). "In this study, we examined expression of AR and VDR, phosphorylation of AKT serine (Ser) 473 (AKT phospho-Ser473) and ERα Ser167 (ERα phospho-Ser167) by immunohistochemistry in ER-positive, HER2-negative early breast cancer." (PMID 29707142, 2018). "The present study demonstrated BRCA1mut breast cancer cases to overexpress VDR, RXR and PPARγ - especially in the absence of ‘classical’ hormone receptors." (PMID 28427429, 2017). "Here, we demonstrate that the VDR can also function in the absence of its ligand to control behaviour of human breast cancer cells both outside and within the bone microenvironment." (PMID 28460457, 2017). "There are several lines of evidence that VDR, RXR or PPARγ may be of relevance in breast cancer tumor-biology." (PMID 28427429, 2017). "Furthermore, we applied an agonist of the vitamin D receptor, paricalcitol, and found that it induced JMJD3 in breast cancer cells." (PMID 28423536, 2017). "Therefore, we analyzed the local expression of β-catenin within mammary tumors of the MMTV-Ron VDR+/+ and VDR−/− mice." (PMID 26008979, 2015). "Though p-values were <0.05 for some tag SNPs and haplotypes in VDR, CYP24A1, and RXRA prior to FDR adjustment, none of the SNPs or haplotypes were significantly associated with breast cancer risk after accounting for FDR." (PMID 26488576, 2015). "Therefore, drugs that target the VDR and EAG1 represent novel approaches to fight against breast cancer." (PMID 25280486, 2014).